INS (insulin)
Diseases named in the same sentence as INS in open-access papers (continued):
Sharing a sentence is not in itself a finding about the gene and the disease.
diabetes (continued). "Type 1 diabetes mellitus (T1D) is characterized by autoimmune destruction of insulin-producing pancreatic ß cells that results in deficient insulin production." (PMID 37402868, 2023). "We found that diabetes, as well as inadequate blood glucose control and initiation of insulin among those with diabetes, were independently associated with an increased rate of HCC among Veterans with existing cirrhosis." (PMID 38055642, 2023). "The American Diabetes Association, the American Association of Clinical Endocrinology, and other references have recommended initiating insulin infusion until the potassium level is > 3.3 mM/L." (PMID 37605707, 2023). "One of the causes of diabetes is insulin resistance, which is associated with a loss of sensitivity to insulin-sensitive cells." (PMID 37153436, 2023). "Factors that were independently associated with a low serum bicarbonate were heart rate, serum potassium, eGFR < 60 mL/min/1.73m2 and history of CHD, while age at diabetes diagnosis, being on insulin therapy and HDL-cholesterol were negatively associated." (PMID 37330446, 2023). "Third, individuals who are genetically susceptible to diabetes show a greater risk of obesity because there is a tendency toward insulin resistance in their skeletal muscle and pancreatic islet β-cells." (PMID 36747216, 2023). "Some investigators have postulated that global migration has led to ethnic differences in insulin sensitivity, and these differences influence the risk of diabetes." (PMID 36636592, 2023). "Unfortunately, insulin therapy increases the risk of excessive glucose fluctuations and hypoglycemia, and these risks are exacerbated in critically ill patients with diabetes." (PMID 37194077, 2023). "Diabetes mellitus is a group of metabolic disorders characterized by hyperglycemia caused by resistance to insulin action, inadequate insulin secretion, or excessive glucagon production." (PMID 36770960, 2023). "Unfortunately, current conventional treatments for diabetes (especially insulin-deficient diabetes) remain insufficient in achieving long-term glycemic control." (PMID 37106373, 2023). "The co-morbidities associated with PCOS not only manifest as anovulatory infertility but also predisposition to metabolic syndrome, type 2 diabetes mellitus, hyperinsulinemia and increased resistance to insulin." (PMID 37854752, 2023). "Diabetes mellitus is a metabolic disease characterized by chronic elevation of blood glucose levels caused by inadequate or defective insulin secretion." (PMID 37883495, 2023). "Insulin resistance refers to a decrease in the efficiency of insulin in promoting glucose uptake and utilization and is associated with metabolic syndrome and type 2 diabetes mellitus (T2DM)." (PMID 37408986, 2023). "Alcohol use [aOR (CI) 1.27 (1.11–1.45)] and diabetes mellitus on insulin [aOR (CI) 2.0 (1.42–2.82)] were unique risk factors for SSI following breast reconstruction." (PMID 36793316, 2023). "Diabetes, a metabolic disease, is characterized by elevated levels of blood glucose caused by defective secretion of insulin and/or impaired biological action of insulin." (PMID 37106373, 2023). "According to the World Health Organization, diabetes, also referred to as diabetes mellitus, is a chronic disease characterized either by a deficient production of insulin or by an ineffective use of insulin." (PMID 37836872, 2023). "While some studies have reported lower levels of zinc among people with diabetes, other reports have also emphasized that zinc deficiency is often associated with a reduced responsiveness to insulin." (PMID 37764713, 2023). "Taking HIV antiretroviral treatment before or concurrently with diabetes treatment and taking metformin in combination with sulphonylurea and/or insulin were associated with the long-term adherence (trajectory D)." (PMID 38127875, 2023). "Type 1 diabetes mellitus (T1D) is a chronic autoimmune disease caused by the destruction of pancreatic insulin-producing beta cells." (PMID 37238221, 2023).
diabetes (continued). "Although controlling glycemic levels in patients with diabetes is crucial, insulin and sulfonylureas can cause hypoglycemic episodes and even potentially fatal events such as comas, seizures, life-threatening arrhythmias, and myocardial infarctions." (PMID 37700268, 2023). "Our top hit, rs3802177 in the SLC30A8 gene is in LD (R2 = 1) with rs13266634, which was associated with diabetes risk in a previous GWAS (as well as in our analysis) and has also been shown to modify insulin secretion." (PMID 37365285, 2023). "In the pancreatic β-cell line, BMAL1 knockdown triggers an increase of the ROS content and impairs glucose-stimulated insulin secretion, the hallmark of the pancreas islet function in diabetes." (PMID 37215098, 2023). "It is implicated in diabetes through carbohydrate dysregulation and inhibition of insulin action, and in hypertension by reducing vasodilation and promoting sympathetic over activity." (PMID 37529617, 2023). "Diabetes is a disease that causes chronic hyperglycemia due to insufficient insulin secretion or insulin action." (PMID 37239172, 2023). "Type 1 diabetes mellitus (T1D) is an autoimmune disease caused by the destruction of insulin-producing β-cells in the pancreas by cytotoxic T-cells." (PMID 38139149, 2023). "Diabetes mellitus (DM) is a chronic disease caused by acquired deficiency in production of insulin by the pancreas, or by the ineffectiveness of the insulin produced." (PMID 36937873, 2023). "According to some studies, vitamin K consumption is associated with improved insulin sensitivity, glucose metabolism, and a lower likelihood of developing diabetes." (PMID 37123774, 2023). "Rarely, SGLT-2is can cause ketoacidosis by increasing glucose excretion and reducing insulin secretion, leading to hyperglucagonemia, which increases the tendency to create ketone bodies." (PMID 37189616, 2023). "Diabetes mellitus is a chronic metabolic disease characterised by an increase in the blood sugar level, caused by insufficient insulin production by the pancreas (type 1 diabetes mellitus) or by insulin resistance in the cells (type 2 diabetes mellitus)." (PMID 36650460, 2023). "Since 1922, insulin administration constitutes the hallmark of therapeutic intervention for diabetes and research has focused on the development of insulin analogs and formulations that act in either a rapid or protracted fashion." (PMID 36792809, 2023). "Reduced Clp function has been linked to increased fasting glucose and insulin levels, potentially indicating a connection between mitochondrial dysfunction and diabetes." (PMID 37960315, 2023). "Previous studies have shown an increased risk of DFUs related to diabetes mellitus duration and insulin therapy duration." (PMID 37510110, 2023). "Diabetes mellitus is a metabolic disorder caused by a defect in insulin secretion, insulin action, or both, resulting in chronic hyperglycemia and interference in the metabolism of carbohydrates, fats, and proteins." (PMID 37233393, 2023). "Instead, dominant mutations leading to early-onset diabetes, called mutant INS-gene-induced diabetes of youth (MIDY), or late-onset diabetes act via a toxic gain-of-function mechanism." (PMID 37283036, 2023). "Previously, we have reported that the combination treatment of gallic acid (20 mg/kg) and andrographolide (10 mg/kg) for 15 days demonstrated synergistic hypoglycemic activity in the streptozotocin (STZ)-induced insulin-deficient diabetes rat model." (PMID 36685073, 2023). "MAPK signals and PI3K/Akt pathways are closely linked to the regulation of insulin sensitivity and have a significant impact on in the pathophysiology of type 2 diabetes mellitus." (PMID 37375718, 2023). "In the DPS, increased fiber intake contributed to a lower risk of T2D, and a metabolite of tryptophan, indolepropionic acid, was directly associated with fiber intake, a lower risk of diabetes, and better insulin secretion." (PMID 36902668, 2023).
diabetes (continued). "Diabetes is characterized by hyperglycaemia associated with impaired insulin signalling and/or insulin secretion." (PMID 36992609, 2023). "Reduced food intake during fasting has been recognized as a contributing factor to hypoglycemia, and this risk is higher in people with diabetes who rely on insulin or antidiabetic medications to manage their condition." (PMID 38169925, 2023). "The American Diabetes Association recommends regular glucose monitoring, insulin administration, nutritional planning, physical activity, and psychological and social support for optimal management of type 1 diabetes in children." (PMID 40303254, 2023). "We found that Wnt pathway–related genes are downregulated with insulin‐deficient diabetes, whereas systemic myostatin inhibition with REGN647 resulted in lower Dkk3 gene expression." (PMID 38025035, 2023). "Diabetes is one of the most common chronic and progressive diseases, as well as a metabolic disorder characterized by hyperglycemia caused by impaired insulin secretion, defective insulin action, or both." (PMID 38784208, 2023). "Insulin regulation is a hallmark of health, and impaired insulin signaling promotes metabolic diseases like diabetes mellitus." (PMID 36730473, 2023). "At the same time, HNF4A polymorphisms are associated with defective insulin secretion, leading to an increased risk of type 2 diabetes mellitus and metabolic syndrome." (PMID 37895816, 2023). "Low-grade chronic inflammation caused by obesity is related to the occurrence of diabetes and is regarded as one of the major causes of insulin resistance in skeletal muscle." (PMID 38027557, 2023). "Diabetes mellitus is a dysregulation of glucose homeostasis either caused by the inability to produce insulin (in Type 1 diabetes) or an insufficient response to insulin (in Type 2 diabetes)." (PMID 37513684, 2023). "Oxidative stress induced by hyperglycemia in diabetes has been implicated in impairing insulin signaling, contributing to the development of insulin resistance." (PMID 38107710, 2023). "T2D accounts for about 80–90% of the cases of diabetes and is due to a progressive loss of β-cell mass and insulin secretion, on the background of insulin resistance (IR), low-grade inflammation, and oxidative stress." (PMID 36675484, 2023). "Diabetes mellitus is a chronic disease that affects the body's metabolism and is defined by hyperglycemia caused by the impairment of insulin secretion, increased peripheral resistance, or both." (PMID 36974247, 2023). "Collectively, GlycA has the capacity to indicate systemic inflammation linked to abnormal insulin biology even preceding early diabetes." (PMID 37814278, 2023). "Mpv17 deficiency was also found to confer resistance to the diabetes induced by an insulin mutation (Ins2Akita), which represents a mouse model of monogenic diabetes characterized by proinsulin misfolding and β-cell failure." (PMID 37522959, 2023). "Diabetes is characterized by a deficiency of the secretion or action of insulin, resulting in microvasculature damage to the retina, renal glomerulus, and heart, as well as peripheral neuropathy." (PMID 36769060, 2023). "Conversely, regular physical activity can improve insulin sensitivity, aid weight management, and reduce the risk of developing both obesity and diabetes." (PMID 37600709, 2023). "In particular, a more flexible treatment strategy is required for glycemic control because of the changes in glucose and insulin metabolism caused by various factors in patients with diabetes undergoing hemodialysis." (PMID 37089609, 2023). "Diabetes severity, conceived as the number of anti-hyperglycemic agents used to treat hyperglycemia, long diabetes duration, need for insulin, and presence of chronic complications, is associated with an increased risk of developing PD." (PMID 38001993, 2023).
diabetes (continued). "Before deterioration of the insulin-resistant state into overt diabetes, there is ensuing hyperinsulinemia which is linked with chronic activation of pro-inflammatory signaling pathways and immune dysregulation." (PMID 38465013, 2023). "The positive association between TG and the risk of incident type 2 diabetes mellitus was possibly due to adverse effect of hypertriglyceridemia on insulin sensitivity and pancreatic beta cell function." (PMID 37790852, 2023). "Insulin, which is synthesized by the islet β cells, is packaged in vesicles and shipped out of the cell, and instability of this system can cause diabetes." (PMID 37153000, 2023). "Diabetes, also known as diabetes mellitus (DM), is an endocrinological condition defined by a fasting blood glucose level greater than 126 mg/dL caused by inadequate or insufficient insulin release from the ß-cells in the Langerhans of the pancreas." (PMID 37964249, 2023). "Aging decreases the ability of pancreatic β-cells to manufacture and secrete insulin and increases the risk of diabetes, reduced vascular distensibility, and increases the risk of hypertension." (PMID 37085806, 2023). "One common manifestation of CF is glycemic dysregulation associated with decreased insulin secretion, often progressing into a distinct form of diabetes known as cystic fibrosis-related diabetes (CFRD)." (PMID 37575762, 2023). "Chronic hyperglycemia, a complex metabolic disorder known as diabetes mellitus (DM), is characterized by deficiencies in insulin secretion, action, or both." (PMID 38313182, 2023). "In rats with diabetes caused by a high-fat diet, biochanin A, a soy isoflavone, reduces insulin resistance through altering the insulin signaling pathway." (PMID 37324738, 2023). "There were also documented demographic factors associated with T2DM and controls, including controlling insulin levels, physical activity, eating habits, and diabetes test results." (PMID 38198642, 2023). "Diabetes is a category of metabolic disorders marked by hyperglycemia caused by problems with insulin secretion, insulin action, or both." (PMID 37287539, 2023). "This approach will allow our group to detect other pathogenic variants causative of monogenic diabetes mellitus and, in case of their absence, discover new genes that play a pivotal role in the release of insulin in response to blood glucose levels." (PMID 36835446, 2023). "In diabetics, the body loses the ability to produce insulin, which is caused by pancreatic β-cell apoptosis or insulin resistance." (PMID 38069300, 2023). "Type 1 diabetes mellitus (T1DM) is a major subtype of diabetes characterized by is insulin deficiency due to the autoimmune destruction of insulin-producing beta cells in the pancreas." (PMID 36768835, 2023). "It is commonly misdiagnosed as T2D and generally treated by oral anti-diabetes medications that cause a delay in commencing insulin therapy." (PMID 36819447, 2023). "The comparison of serum insulin levels in different groups showed that STZ-induced diabetes caused damage to pancreatic beta cells and reduced blood insulin levels." (PMID 38113243, 2023). "We conclude that the protective INS variant further decreases the low risk for diabetes complications accomplished through intensive insulin treatment and glycemic control in patients with European ancestry." (PMID 36701305, 2023). "Diabetes mellitus is a multifactorial disease caused by multiple genetic factors leading to decreased insulin secretion and sensitivity, in addition to lifestyle factors such as overeating and lack of exercise." (PMID 38027100, 2023). "The reason STZ causes diabetes is that it is employed preferentially for the degeneration of insulin generating β-cells, which ultimately leads to the development of necrosis." (PMID 37936909, 2023). "Lowered levels of Glu-2 have been previously associated with increased inflammation and reduced insulin sensitivity in an experimental model of diabetes." (PMID 37808009, 2023).
diabetes (continued). "To confirm that TyG index is particularly well related to IR in patients with diabetes, we evaluated the association between other simultaneously measured IR or insulin sensitivity indices and TyG index." (PMID 36793475, 2023). "The model also reproduces the hyperglucagonemia, which is experienced by diabetes patients, and it is linked to a failure of insulin to inhibit α-cell activity." (PMID 37645413, 2023). "Lifestyle interventions and metabolic surgery can remit diabetes by improving insulin sensitivity and preserving islet β-cell function through weight loss, whereas insulin-intensive therapy can remit diabetes by protecting only the islet β-cell function." (PMID 37814256, 2023). "T1DM results from uncontrolled and extended immune responses of immune cells on β-cells, and resultant diabetes progresses due to the gradual loss of insulin-producing cells." (PMID 36911496, 2023). "Depending on the etiology, diabetes has been classified broadly into type 1 diabetes mellitus (T1DM), resulting from a deficiency in insulin production, and type 2 diabetes mellitus (T2DM), a defect in insulin action." (PMID 36627919, 2023). "Diabetes is a chronic metabolic disorder characterized by high blood glucose levels resulting from a deficiency in insulin secretion or its inability to function effectively." (PMID 38067527, 2023). "The dysfunction of microglia in the development of diabetes is associated with various diabetic complications, while traditional insulin therapy is insufficient to rapidly restore the function of microglia." (PMID 38066234, 2023). "Since insulin is the major cause of hypoglycemia in diabetic patients, our study aims to assess the knowledge about hypoglycemia and its management among insulin-dependent diabetes mellitus patients in Al-Ahsa, Saudi Arabia." (PMID 37859676, 2023). "Gla-300 is a second-generation basal insulin with proven benefits of reduced risk of hypoglycemia and improved glycemic control in special populations of people with diabetes." (PMID 36624651, 2023). "The higher prevalence of some variables in women can be explained by hormonal changes, for example, affecting how their bodies use insulin, which puts them at a higher risk of developing diabetes and also blood pressure can be affected by weight gain." (PMID 37152229, 2023). "Taken together, our findings indicate that combined Yijinjing and resistance training is effective in alleviating insulin resistance and liver injury in elderly pre-diabetes, which is associated with the inhibition of NLRP3 inflammasome activity." (PMID 36817440, 2023). "Type 2 diabetes mellitus (T2DM) is associated with alterations in oxidative metabolism in insulin-responsive tissues." (PMID 38313834, 2023). "It is caused by the long-term effects of diabetes mellitus, which can result from resistance to insulin (hyperglycemia) in type 2 diabetes or autoimmune destruction of insulin-producing cells in type 1 diabetes." (PMID 37420558, 2023). "Diabetes is characterized by insulin resistance and insufficient insulin secretion, which is caused by obesity, metabolic syndrome, impaired β-cell function and other risk factors." (PMID 37344885, 2023). "In its guideline, the American Diabetes Association (ADA) states that basal insulin or basal-corrected insulin regimen plus a bolus is a therapeutic option for hospitalized patients who are not seriously ill." (PMID 37168726, 2023). "On the other hand, Coriandrum sativum L. restored body weight loss during diabetes, which can be because of its ability to improve insulin sensitivity and decrease lipids and glucose levels." (PMID 37432178, 2023). "In our study, we treated female mice with STZ to recapitulate several known metabolic characteristics in diabetes, including hyperglycemia, weight loss, depletion in insulin and estrogen levels, and elevation in the level of oxidative stress marker MDA." (PMID 36979006, 2023).